SIRT3 (sirtuin 3)
Diseases named in the same sentence as SIRT3 in open-access papers (continued):
Sharing a sentence is not in itself a finding about the gene and the disease.
Hepatic steatosis (46 papers, 2011 to 2025). Steatosis is a term used to denote lipid accumulation within hepatocytes. "A prior research similarly showed that the main cause of the chronic hepatic steatosis and inflammation that results in cardiovascular damage under HS loading is SIRT3 suppression induced by histone modification." (PMID 36386919, 2022). "Sirt3-deficient mice show higher levels of fatty acid β-oxidation intermediate products and triglycerides in the liver during fasting and develop hepatic steatosis." (PMID 30574122, 2018). "In addition to its mitochondrial effects, hepatic SIRT3 deficiency exacerbated hepatic steatosis in HFD mice by upregulating proteins associated with FA uptake, including CD36 and VLDL receptors." (PMID 37507803, 2023). "Recent studies have found an association with the decrease in SIRT3 activity and hepatic steatosis." (PMID 35805129, 2022). "In addition, SIRT3 downregulation seems to also be associated with high lipid levels such as in the liver tissue of fatty liver mouse models or patients with fatty liver disease." (PMID 35453391, 2022). "Here, we present evidence that Sirt3 deficiency in the context of an excess of lipids exacerbates hepatic steatosis through different new mechanisms, thus affecting the expression of transcriptional co-activators involved in fatty acid oxidation and of genes involved in lipid uptake." (PMID 32912335, 2020). "Additional mechanisms, including lipogenesis, may play a role aggravating hepatic steatosis in Sirt3-deficient mice fed the HFD compared to WT mice." (PMID 32912335, 2020). "In this study, we investigated additional mechanisms that might play a role in aggravating hepatic steatosis in Sirt3-deficient mice fed a high-fat diet (HFD)." (PMID 32912335, 2020). "In this study, we show that Sirt3 deficiency aggravates HFD-induced hepatic steatosis through a new mechanism that prevents the adaptive increase in the hepatic levels of proteins involved in fatty acid oxidation observed in WT mice fed the HFD, such as LIPIN1." (PMID 32912335, 2020). "Interestingly, the hepatic deficiency of SIRT1 as well as the whole body deletion of SIRT3 have been linked to increased susceptibility to hepatic steatosis and related metabolic complications." (PMID 31541116, 2019). "Sirt3-knockout mice reportedly develop fatty liver, glucose intolerance and decreased respiratory function, and the phenotype of these mice is similar to that of Hint2−/− mice." (PMID 40307568, 2025). "SIRT3 also controls lipid metabolism, including suppressing lipogenesis and lipid accumulation, as well as promoting fatty acid β-oxidation, hepatic steatosis, and lipid mobilization." (PMID 39372420, 2024). "In a hepatic steatosis model in postnatal overfed rats, dietary curcumin improved hepatic steatosis and mitochondrial function via SIRT3 activity." (PMID 37630770, 2023). "HADHA is a substrate widely regulated by SIRT3, and its 5 acetylation sites were significantly differentially acetylated among three hepatic steatosis groups (P < 0.05)." (PMID 37568219, 2023). "When fed a HFD, Sirt3 knockout (KO) mice develop hepatic steatosis and have diminished beta-oxidation gene activation compared to wild-type (WT) controls." (PMID 35805129, 2022). "The injury of mitochondrial biosynthesis and antioxidant response aggravates the severity of NAFLD induced by HFD, while pharmacological stimulation of SIRT3 expression can improve mitochondrial function and reduce hepatic steatosis." (PMID 36008973, 2022). "Deficiency of mitochondrial sirtuin 3 (SIRT3), a NAD+-dependent protein deacetylase that maintains redox status and lipid homeostasis, contributes to hepatic steatosis." (PMID 32912335, 2020). "SIRT3 mediated DHY-induced amelioration of hepatic steatosis and oxidative injury by improving mitochondrial functions." (PMID 32933152, 2020).
Hepatic steatosis (continued). "Theacrine ameliorated acylcarnitine metabolism disorder in high-fat diet (HFD)-fed mice, resulting in suppression of hepatic steatosis and liver inflammation and improvement of energy expenditure through the SIRT3/LCAD signaling pathway." (PMID 33392238, 2020). "NNMT overexpression, in conjunction with elevated NAM levels, augments hepatic steatosis by inhibiting Sirt3 activity." (PMID 29872122, 2018). "Partial PNO replacement in the HFD ameliorated hepatic steatosis and prevented the down-regulation of SIRT3 in white adipose tissue." (PMID 26805879, 2016). "This is in agreement with our data that showed liver-specific knockout of Mfn2 in mice is linked to impaired glucose metabolism, to decreases in SIRT1, SIRT3, and insulin signaling resulting in hepatic steatosis." (PMID 28097021, 2016). "Our findings are consistent with recent studies implicating SIRT3 as a key player in fatty liver disease pathogenesis." (PMID 27040510, 2016). "In this way, SIRT1 and SIRT3 are involved in the balance of metabolic and hepatic steatosis regulation through the epigenetic modification." (PMID 25751727, 2015). "Uridine co-administration was less effective in Sirt3-KO mice in preventing fenofibrate-induced fatty liver." (PMID 24475249, 2014). "However, another study found that high NNMT expression causes fatty liver disease by modulating the NAD level that, in turn, regulates SIRT3." (PMID 36750850, 2023). "Caffeine was another important bioactive compound in coffee and could suppress hepatic steatosis by activating SIRT3-AMPK-ACC and signal transducer and activator of transcription 3 (STAT3) pathways." (PMID 33728021, 2021). "For example, mammalian sirtuins (SIRTs), NAD-dependent histone deacetylase such as SIRT1 and SIRT3, were involved in oxidative stress and lipid metabolism regulation, and had been proposed as a reliable biomarker and/or therapeutic target for fatty liver disease." (PMID 34481473, 2021). "In line with previous studies, HFD-induced hepatic steatosis was aggravated in Sirt3−/− mice." (PMID 32912335, 2020). "Chronic HFD feeding would reduce SIRT3 levels, which in turn would result in hyperacetylation and a subsequent decrease in the activity of enzymes involved in mitochondrial β-oxidation, thus leading to hepatic steatosis." (PMID 32912335, 2020). "Next, we examined whether increased lipogenesis was also involved in the exacerbation of hepatic steatosis in Sirt3−/− mice fed the HFD." (PMID 32912335, 2020). "Sirt3−/− mice fed a HFD presented exacerbated hepatic steatosis that was accompanied by decreased expression and DNA-binding activity of peroxisome proliferator-activated receptor (PPAR) α and of several of its target genes involved in fatty acid oxidation, compared to WT mice fed the HFD." (PMID 32912335, 2020). "Mammalian sirtuins (SIRTs) is an important type of NAD-dependent histone deacetylase, such as SIRT1 and SIRT3, were involved in oxidative stress and lipid metabolism regulation, and had been proposed as a reliable biomarker and/or therapeutic target for fatty liver disease." (PMID 32586350, 2020). "Moreover, recent findings have shown that SIRT3, a mitochondrial protein deacetylase, is down-regulated in response to maternal fat exposure and is involved in the development of fatty liver disease." (PMID 27040510, 2016). "SIRT3 knockout mice developed hepatic steatosis and IR in the mice fed with HFD." (PMID 25751727, 2015). "However, it is currently unknown whether Sirt3 prevents hepatic steatosis in mice fed the HFD through additional mechanisms." (PMID 32912335, 2020). "Sirt3 overexpression effectively decreased body weight gain, serum AST and ALT levels and intrahepatic TG content, ameliorated hepatic steatosis and reversed mitochondrial structural damage in HFD-fed Hint2−/− mice." (PMID 40307568, 2025).
Hepatic steatosis (continued). "Higher NAD+ levels can enhance the activity of sirtuin 1 (SIRT1) and sirtuin 3 (SIRT3), which have been reported to protect mice from fatty liver diseases such as NAFLD." (PMID 38786029, 2024). "At the same time, in HFD-induced NAFLD rats, BBR-induced activation of SIRT3, a crucial gene for fatty acid oxidation, alters the expression of ACC and carnitine palmitoyltransferase-1A (CPT-1A), thereby reducing hepatic steatosis." (PMID 38034996, 2023). "SIRT2, SIRT3, and SIRT4 upregulation induced by an investigational molecule also prevented the progression of hepatic steatosis and fibrosis in obese rats." (PMID 35203484, 2022). "Overexpression of SIRT3 significantly decreases the acetylation of MTP, increases mitochondrial FAO, and decreases hepatic steatosis, CD68, and serum ALT levels." (PMID 36008973, 2022). "Theacrine inhibited hepatic steatosis and liver inflammation, improved energy expenditure and ameliorated acylcarnitine metabolism disorder in HFD-fed mice through SIRT3/LCAD signaling pathway." (PMID 33392238, 2020). "Compared with WT, MTP+/− mice displayed reduced hepatic SIRT3 levels and reduced FAO, with increased hepatic steatosis and the inflammatory marker CD68." (PMID 29581157, 2018). "Overexpression of SIRT3 in MTP+/− mice significantly reduced the acetylation of MTP compared with β-galactosidase controls, increased mitochondrial FAO, and reduced hepatic steatosis, CD68, and serum ALT levels." (PMID 29581157, 2018). "SIRT3 is a mitochondrial NAD+-dependent deacetylase that controls the acetylation status of many enzymes and proteins involved in energy metabolism, impacting lipogenesis, fatty acid β-oxidation, hepatic steatosis, lipid accumulation, and lipid mobilization." (PMID 39372420, 2024). "Our results suggested that SIRT3 expression was downregulated by a high-fat diet, but was restored by the co-administration of CEL or COT extract in both in vitro and in vivo studies, indicating a protective role of SIRT3 against fatty liver disease." (PMID 39161898, 2024). "Although the acetylation status of many substrates of SIRT3 was significantly altered in the hepatic steatosis group in this study, the expression of SIRT3 did not explain these changes." (PMID 37568219, 2023). "Collectively, these results suggested that HK alleviates liver steatosis in CDHFD-fed mice, which might be mediated through the SIRT3-AMPK axis." (PMID 34758848, 2021). "The decrease in SIRT3 levels might activate an adaptive mechanism through the increase in nuclear HIF-1α and LIPIN 1 levels to attenuate hepatic steatosis." (PMID 32912335, 2020). "This indicates that the absence of SIRT3 accelerates fatty acid accumulation and liver hepatic steatosis." (PMID 32912335, 2020). "Thus, exosomes could inhibit SIRT3 and autophagy by delivering miR-421 to macrophages and promote M1 polarization in vivo, thereby participating in OSA-induced liver steatosis." (PMID 38764033, 2024). "Therefore, the components of OSA-derived exosomes may increase the level of NLRP3 inflammasomes by inhibiting the SIRT3/AMPK pathway in macrophages, thereby promoting M1 polarization and liver steatosis." (PMID 38764033, 2024). "Notably, experiments on animals lacking SIRT3 and fed a high-fat diet reveal more severe hepatic steatosis compared to wild-type mice." (PMID 39081807, 2024). "However, the expression of SIRT3 was not significantly different among the hepatic steatosis groups by proteomic analysis." (PMID 37568219, 2023). "In addition, mice lacking Sirt3 fed a high-fat diet (HFD) show enhanced hepatic steatosis compared to wild-type (WT) mice, a finding consistent with the hyperacetylation and reduced activity of enzymes involved in mitochondrial fatty acid oxidation." (PMID 32912335, 2020).
endothelial dysfunction (43 papers, 2015 to 2025). In vascular diseases, endothelial dysfunction is a systemic pathological state of the endothelium (the inner lining of blood vessels) and can be broadly defined as an imbalance between vasodilating and vasoconstricting substances produced by (or acting on) the endothelium. "In general, SIRT3 inhibition causes endothelial dysfunction and worsens endothelial inflammation in the presence of proinflammatory stimuli." (PMID 38233193, 2024). "Sirt3-deficient mice fed a high-cholesterol diet exhibit impaired superoxide-dependent endothelial dysfunction." (PMID 36675125, 2023). "Studies also reported that Sirt3 deficiency induces endothelial dysfunction in different model of disease." (PMID 37816025, 2023). "For example, endothelial SIRT3 deficiency in obese mice worsened endothelial dysfunction and promoted transforming growth factor β-induced EndoMT." (PMID 37237500, 2023). "Given these premises, we sought to investigate if a disbalance in production or elimination of ROS is a hallmark feature associated with endothelial dysfunction in Sirt3-/- mice." (PMID 37816025, 2023). "Here, we found that whole body Sirt3-deficient mice exhibited reduced renal capillary density, reflecting endothelial dysfunction, and VEGFA expression compared to wild-type mice." (PMID 37816025, 2023). "The same study found that a loss of SIRT3 activity in mice also promotes hyperlipidemia, inflammation and endothelial dysfunction." (PMID 34829803, 2021). "This implies that spironolactone ameliorated the AGEs/RAGE associated endothelial dysfunction through the upregulation of SIRT3." (PMID 31492107, 2019). "A possible mechanism is that SIRT3 deficiency-induced metabolic dysfunction and an increase in ROS in ECs result in endothelial dysfunction which limits coronary blood flow in response to increased metabolic demand or ischemia." (PMID 30873415, 2019). "AGEs have been recently reported to decrease SIRT3 levels and SIRT3 knock down was associated with endothelial dysfunction in endothelial progenitor cells (EPCs)." (PMID 29085333, 2017). "Taken together, Sirt3 deficiency induces a mild, superoxide-dependent endothelial dysfunction in mice fed a high-cholesterol diet." (PMID 27071400, 2016). "Sirt3 deficiency may result in mitochondrial protein hyperacetylation, promoting endothelial dysfunction, increasing smooth muscle cell hypertrophy, inducing vascular inflammation, and triggering age-dependent hypertension." (PMID 39060773, 2024). "Moreover, upregulation of Angpt-2 expression in Sirt3 deficient mice, accelerated angiotensin-II-induced endothelial dysfunction in the kidney and exacerbated ROS formation." (PMID 37816025, 2023). "Redox changes at the mitochondrial level and deficiency of SIRT3 have been associated with metabolic pathologies and endothelial dysfunction, thus increasing the interest toward the identification of mitochondrial targets and their involvement in chronic diseases." (PMID 37372041, 2023). "Taken together, SIRT3 deficiency may be the cause of endothelial dysfunction by reducing the expression of PFKFB3, reprogramming EC metabolisms and promoting inflammation." (PMID 30873415, 2019). "The aim of the present study is to evaluate the impact of global Sirt3 deficiency on renal endothelial cell phenotype and to investigate whether SIRT3 deficiency impacts on endothelial dysfunction and on the severity of renal injury induced by the nephrotoxic agent Adriamycin (ADR)." (PMID 37816025, 2023). "While these studies clearly suggest the critical role of SIRT3 on endothelial cell function, scarce literature is available documenting the underlying molecular mechanism and the actual impact of SIRT3 deficiency on endothelial dysfunction and on the progression of diseases affecting the kidney." (PMID 37816025, 2023).
endothelial dysfunction (continued). "In contrast, the levels of NADPH oxidase (p47phox and gp91phox) and ROS formation were upregulated in SIRT3KO mice, suggesting that deficiency of SIRT3 reduced glucose metabolism and enhanced ROS formation which may result in endothelial dysfunction in the kidneys." (PMID 33233553, 2020). "To further examine the role of SIRT3 in endothelial dysfunction caused by MICU1 depletion, we silenced SIRT3 in HAECs." (PMID 40166941, 2025). "Conversely, transgenic mice with global Sirt3 overexpression are protected from endothelial dysfunction, vascular oxidative stress, and hypertrophy." (PMID 36675125, 2023). "In part, that endothelial dysfunction is related to depletion of Sirt3 (a protein essential for mitochondrial health) and mitochondrial ROS generation." (PMID 36139783, 2022). "Overexpression of SIRT3 in mice protects against endothelial dysfunction and attenuates vascular oxidative stress in experimental hypertensive mouse models." (PMID 35453391, 2022). "It was reported that SIRT3 involved in the regulation of endothelial dysfunction and affecting the development of hypertensive cardiovascular diseases." (PMID 34180125, 2021). "SIRT3 protects the heart from endothelial dysfunction through the regulation of oxidative stress and metabolic reprogramming." (PMID 34180125, 2021). "On the same note, in vitro hyperlipidemia inhibits monocytic SIRT3, which leads to autophagy, mitophagy and decreased levels of endothelial adhesion molecules, thus contributing to endothelial dysfunction, inflammation and atherogenesis." (PMID 34829803, 2021). "SIRT3 deficiency and redox inactivation of SIRT3 result in SOD2 inactivation and contribute to the pathogenesis of endothelial dysfunction and hypertension." (PMID 32015327, 2020). "The study suggested DHY improved endothelial dysfunction in diabetic mice via oxidative stress inhibition in a SIRT3-dependent manner." (PMID 32933152, 2020). "Recently, Liu and colleagues demonstrated that SIRT3 binds with ATG5 and deacetylates it, while SIRT3-deficient macrophages display impaired autophagy, leading to accelerated NLRP3 inflammasome activation and endothelial dysfunction." (PMID 30574122, 2018). "Collectively, all these data indicated that mtROS is involved in the regulation of SIRT3 on endothelial insulin sensitivity and SIRT3 protects against HFD-induced endothelial dysfunction by inhibiting mtROS increase." (PMID 27000941, 2016). "Overexpression of SIRT3 improves endothelial insulin sensitivity and attenuates endothelial dysfunction induced by nutrient excess through inhibiting mitochondrial oxidative stress." (PMID 27000941, 2016). "The in vitro findings suggest that a novel C/EBP-β-dependent rescue mechanism diminishes Sirt3-dependent endothelial dysfunction under physiological conditions (normal diet)." (PMID 27071400, 2016). "This could be due to the fact that the global knockout of Sirt3 may yield mixed results beyond regulating endothelial dysfunction." (PMID 40166941, 2025). "In addition, it was reported that SIRT3 upregulation attenuates AngII-induced hypertrophy by inhibiting vascular oxidative stress and endothelial dysfunction." (PMID 39300372, 2024). "Our previous data have shown that PCSK9 caused inflammatory stress and endothelial dysfunction, and that the pleiotropic protective effects of i-PCSK9 in EC might be mediated, at least in part, by NAD-dependent deacetylase SIRT3." (PMID 37587410, 2023). "In addition, our previous investigations demonstrated that superoxide dismutase 2 (SOD2) as a down-stream target of SIRT3 participated in the protective effect of endothelial dysfunction in diabetic mice by DHY." (PMID 36671063, 2023). "Systemic Sirt3 knockout mice develop endothelial dysfunction." (PMID 35923237, 2022). "In addition, cigarette smoke, a validated risk factor for CVD, decreases endothelial SIRT3 levels and leads to SOD2 hyperacetylation and endothelial dysfunction." (PMID 34829803, 2021).